OSTM1 (osteoclastogenesis associated transmembrane protein 1)
Diseases named in the same sentence as OSTM1 in open-access papers (continued):
Sharing a sentence is not in itself a finding about the gene and the disease.
gastric cancer (continued). "OSTM1 was significantly overexpressed in gastric-cancer tissues, negatively correlating with TNM staging and overall survival." (PMID 39852172, 2025). "More gastric-cancer tissue specimens need to be collected to assess the correlation between OSTM1 expression and patient prognosis and to explore its potential as a molecular marker." (PMID 39852172, 2025). "We analyze the expression and correlation of OSTM1 and S100A4 in gastric-cancer tissues through clinical samples and explore the regulatory effects of OSTM1 on S100A4 expression using in vitro cell experiments and in vivo animal models." (PMID 39852172, 2025). "In gastric-cancer cell models, cells overexpressing OSTM1 exhibited higher invasive and migratory capabilities, while these effects were significantly attenuated after S100A4 knockdown." (PMID 39852172, 2025). "Further in vivo and in vitro experiments confirmed that OSTM1 promotes the proliferation, migration, and invasion abilities of gastric-cancer cells by enhancing the expression and activity of S100A4." (PMID 39852172, 2025). "OSTM1 represents a potential diagnostic and prognostic biomarker, with the OSTM1–S100A4 axis offering new therapeutic possibilities for gastric-cancer treatment." (PMID 39852172, 2025). "Real-time quantitative PCR (RT-qPCR) and Western blot were used to detect the mRNA and protein expression levels of OSTM1 in two gastric-cancer cell lines, MGC803 and AGS." (PMID 39852172, 2025). "OSTM1 expression was analyzed in gastric-cancer and adjacent tissues using immunohistochemistry and RT-qPCR." (PMID 39852172, 2025). "In conclusion, S100A4 is a key molecule for OSTM1 to exert its promoting effect on gastric-cancer invasion and metastasis." (PMID 39852172, 2025). "This suggests that OSTM1 may play a promoting role in the occurrence and development of gastric cancer." (PMID 39852172, 2025). "In this study, we investigated the role of OSTM1 in gastric cancer and its potential mechanisms." (PMID 39852172, 2025). "This study explores OSTM1’s role in gastric-cancer proliferation and metastasis." (PMID 39852172, 2025). "This suggests that S100A4 mediates the role of OSTM1 in promoting gastric-cancer lung metastasis." (PMID 39852172, 2025). "Therefore, investigating the impact of OSTM1 on fibroblast activation during gastric-cancer lung metastasis is of great significance." (PMID 39852172, 2025). "Moreover, whether OSTM1 regulates other signaling pathways during the development and progression of gastric cancer is also worth further exploration." (PMID 39852172, 2025). "The results showed that compared with the control group (sh-NC), the number of α-SMA+ and CD31+ cells in lung metastases of OSTM1 knockdown-group (sh-OSTM1) mice was significantly reduced, suggesting that the knockdown of OSTM1 could inhibit angiogenesis in gastric-cancer lung metastases." (PMID 39852172, 2025). "Compared with the control group (OE-NC), the number of α-SMA+ and CD31+ cells in lung metastases of OSTM1 overexpression-group (OE-OSTM1) mice was significantly increased, indicating that the overexpression of OSTM1 could promote angiogenesis in gastric-cancer lung metastases." (PMID 39852172, 2025). "The ridgeline plot results show that OSTM1 and S100A4 have a co-expression trend in the gastric-cancer data analysis." (PMID 39852172, 2025). "Although existing research has revealed the potential roles of OSTM1 and S100A4 in tumor development, their specific interactions and mechanisms in gastric cancer remain unclear." (PMID 39852172, 2025). "Additionally, this study examines potential therapeutic strategies targeting the OSTM1/S100A4 signaling pathway, providing new insights and approaches for the treatment of gastric cancer." (PMID 39852172, 2025). "This suggests that OSTM1 may positively regulate S100A4 expression, and the two may play a synergistic role in the metastasis of gastric cancer." (PMID 39852172, 2025).
gastric cancer (continued). "These in vivo experimental results support the inference that OSTM1 positively regulates S100A4 expression, which may affect gastric-cancer lung metastasis." (PMID 39852172, 2025). "Furthermore, we also explored the role of OSTM1 and S100A4 in the gastric-cancer microenvironment." (PMID 39852172, 2025). "By investigating the roles of OSTM1 and S100A4 in gastric cancer, this study not only aids in understanding the molecular pathophysiology of gastric cancer but may also offer new molecular targets for targeted therapy, holding significant scientific value and clinical implications." (PMID 39852172, 2025). "In summary, this study systematically confirms that OSTM1 may play an important role in the progression and metastasis of gastric cancer by positively regulating S100A4 expression from multiple levels, including gastric-cancer patient samples, in vitro cells, and animal models." (PMID 39852172, 2025).
lentivirus infection (1 paper, 2023). Virus diseases caused by the Lentivirus genus. "To determine where OSTM1 protein is distributed in mature osteoclasts, we overexpressed HA-tagged OSTM1 and c-Myc tagged CLC7 in osteoclast precursors by lentivirus infection and differentiated the transduced cells into multinuclear osteoclasts in bone slices." (PMID 37106712, 2023).
neuropathy (1 paper, 2021). A disorder affecting the nervous system that manifests with pain, tingling, numbness, and/or muscle weakness. "Loss-of-function and in some cases also gain-of-function of the intracellular CLCs, ClC-3/ClC-4, ClC-6 and ClC-7/Ostm1, lead to neuropathies, often neurodegeneration." (PMID 33708769, 2021). "Dominant CLCN7 mutations, which may lead to subcellular mislocalization of the ClC-7/Ostm1 complex or the impingement of the dysfunctional subunit on the ion transport properties of the unaffected subunit, do not lead to neuropathy in mild ADO2." (PMID 33708769, 2021).
osteosarcoma (1 paper, 2024). A usually aggressive malignant bone-forming mesenchymal neoplasm, predominantly affecting adolescents and young adults. "We coexpressed WT or K285T mutant ClC-7 with OSTM1-red fluorescent protein (RFP) in an osteosarcoma U2OS cell line that constitutively expressed LAMP1-GFP to assess the influence of the K285T variant on lysosome morphology." (PMID 38838776, 2024).
retinal degeneration (1 paper, 2017). Degeneration of the retina. "Although previously the blindness was believed to be the result of osteopetrotic narrowing of the optic nerve canal, retinal degeneration is a direct effect of disruption of ClC-7 or Ostm1 at retinal neurons." (PMID 28386229, 2017).
cancer (1 paper, 2025). A tumor composed of atypical neoplastic, often pleomorphic cells that invade other tissues. "OSTM1 overexpression enhanced cancer-cell proliferation, colony formation, migration, and invasion, while its knockdown showed opposite effects." (PMID 39852172, 2025). "OSTM1 overexpression and knockdown cell lines were established to assess its effects on cancer-cell behavior through in vitro and in vivo experiments." (PMID 39852172, 2025).
tumor (1 paper, 2025). "Recent studies have shown that OSTM1 is abnormally expressed in various tumors and may be associated with tumor aggressiveness and metastatic potential." (PMID 39852172, 2025). "The study found that OSTM1 directly acts on tumor cells but also indirectly promotes tumor proliferation and metastasis by influencing cells in the tumor microenvironment, such as fibroblasts and endothelial cells." (PMID 39852172, 2025). "For example, OSTM1 can enhance the activity of fibroblasts, promoting their secretion of factors that stimulate tumor growth and angiogenesis." (PMID 39852172, 2025). "For instance, OSTM1 is highly expressed in cells and closely related to tumor aggressiveness and prognosis." (PMID 39852172, 2025). "This suggests that OSTM1 may be a molecular marker generally involved in tumor development." (PMID 39852172, 2025).
OSTM1 also shares sentences with these, for which no sentence is quoted: lysosomal storage disease (3 papers); B-cell non-Hodgkin lymphoma (1); Bartter syndrome (1); Dent disease (1); depression (1); hypoparathyroidism (1); leukodystrophy (1); Myotonia congenita (1); neurological disorders (1); neuronal ceroid lipofuscinosis (1); ovarian carcinoma (1).